PRMT5 (protein arginine methyltransferase 5)
Diseases named in the same sentence as PRMT5 in open-access papers (continued):
Sharing a sentence is not in itself a finding about the gene and the disease.
lung carcinoma (continued). "Since both MP and PRMT5 showed an alteration in their regulatory phosphorylation by Proteome Profiler tissue array screening in several cancer types, we aimed to investigate the expression and modifications of the elements of the PPM1B/MP/PRMT5 pathway in different histological types of lung cancer." (PMID 41301499, 2025). "Interestingly, a significant rise in p21 levels was also found in PRMT5-inhibited cells, implying that unmethylated FXR1 may be dormant in both oral and lung cancer cells." (PMID 38709899, 2024). "Besides, circ-PRMT5 could effectively sponge miR-498 to alleviate its repression on the well-known oncogenic EZH2, thereby facilitating lung cancer progression." (PMID 32541093, 2020). "The identification of PRMT5 and PRMT1 as CFLARL regulators involved in cellular apoptosis may help in developing new strategies to increase the sensitivity of cancer cells to chemotherapy, which may eventually benefit lung cancer treatments." (PMID 30736843, 2019). "However, compounds C9 and C9a failed to inhibit such phosphorylation events in A549 cells (lanes 2 and 3), suggesting that compounds C9 and C9a inhibit growth of lung cancer cells not through targeting CDKs rather than a direct consequence of PRMT5 inhibition." (PMID 28806746, 2017). "But additional gene products that interact genetically or biochemichally with PRMT5 and WDR77 in the control of lung cancer cell growth are not characterized." (PMID 26988096, 2016). "Immunoblot experiments showed abundant expression of PRMT5 and its symmetric methylation mark H4R3 in lung carcinoma but not in non-neoplastic human pulmonary alveolar and bronchial epithelial cell lines." (PMID 24326178, 2013).
glioblastoma (82 papers, 2013 to 2026). The most malignant astrocytic tumor (WHO grade IV). "Glioblastoma is also associated with overexpression of PRMT5, which is correlated with cell growth rate." (PMID 40869229, 2025). "It is worth noting that downregulation of PRMT5 in IDH-mutant WHO G4 astrocytomas or IDH-wildtype glioblastomas is associated with a more favorable prognosis." (PMID 38827324, 2024). "Mechanistically, suppression of protein arginine methyltransferase 5 (PRMT5) attenuates the expression of RNF168 in methylthioadenosine phosphorylase (MTAP)-deficient glioblastoma cells, contributing to the destabilization of H2AX by SMURF2." (PMID 36694209, 2023). "Nevertheless, baseline differences in the top 45 differential splicing events in glioblastoma can form a splicing signature that seems to differentiate between good and poor responders to PRMT5 inhibition better than mutational status." (PMID 34680285, 2021). "The prevalence of cellular signaling GO terms parallels a finding in glioblastoma, where genes with a decrease in detained introns regulated by PRMT5 are also associated with perturbed kinase signaling." (PMID 32188845, 2020). "Recently, PRMT5 was found to associate with aberrant MYC function in various cancers including brain tumors such as glioblastoma and neuroblastoma." (PMID 31694585, 2019). "The aberrant expression of PRMT5 has been associated with a variety of cancers including glioblastoma and neuroblastoma." (PMID 31694585, 2019). "PRMT5 deficiency also led to apoptosis in differentiated glioblastoma cells however, in glioblastoma neurospheres it led to G1 cell cycle arrest through increased protein expression of p27 and a decrease in phosphorylation of pRb." (PMID 29568320, 2018). "In our previous study, we and others have shown that the PRMT5 that is overexpressed in glioblastoma inversely correlates with patient survival, and inhibition of PRMT5 caused apoptosis in differentiated glioblastoma tumor cells and senescence in stem-like glioblastoma tumor cells." (PMID 39989968, 2025). "Additionally, elevated levels of PRMT5 have been associated with enhanced invasion of glioblastoma cells." (PMID 39043634, 2024). "Additionally, PRMT1 and PRMT5 expression has been associated with the development of glioblastoma and medulloblastoma." (PMID 38183103, 2024). "Although there have been some preliminary reports of an association between c-Myc and PRMT5 in neuroblastoma cells and glioblastoma cells 47, 48, this is the first report of the mechanism and significance of c-Myc interaction with PRMT5 in gastric cancer cells." (PMID 32292506, 2020). "We consistently found an association between Myc or Omomyc and PRMT5 in glioblastoma cells." (PMID 26563484, 2015). "For instance, the specific PRMT5 inhibitor EPZ015666 has been shown to overcome resistance to mTOR inhibitors in glioblastoma." (PMID 41513606, 2026). "For example, our group was among the first to show that protein arginine methyltransferase 5 (PRMT5) inhibition in glioblastoma neurospheres responds to trametinib (MEK1/2 inhibitor) both in vitro and in vivo." (PMID 40725122, 2025). "Protein Arginine Methyltransferase 5 (PRMT5) is overexpressed in glioblastoma and its inhibition imparts an anti-tumor effect." (PMID 39989968, 2025). "As PRMT5 is a druggable target, several PRMT5 inhibitors including LLY-283 are under investigation for treating glioblastoma." (PMID 39989968, 2025). "To test if PRMT5 alters the effect of TMZ in glioblastoma, we used GBMNS that are relatively TMZ-resistant (GSC040815 and GSC082209) and TMZ-sensitive (GBM12 and GBM43)." (PMID 39989968, 2025). "Collectively, these findings indicate the potential of combination therapies with PRMT5 inhibitors and highlight their potential in transforming strategies directed toward glioblastoma treatment." (PMID 40450009, 2025).
glioblastoma (continued). "We demonstrated that PRMT5 depletion enhanced trametinib-induced cytotoxicity in glioblastoma as well as decreased trametinib-induced AKT and ERBB3 escape pathway activity." (PMID 40725122, 2025). "Combination therapy with both PRMT5 depletion and trametinib prolonged overall survival in our intracranial glioblastoma xenograft mouse models." (PMID 40725122, 2025). "For instance, PRMT5 represses PTEN expression at the transcriptional level in glioblastoma neurospheres (GBMNSs) by binding to its promoter." (PMID 40243588, 2025). "LLY-283 is a selective SAM-competitive nucleoside inhibitor of PRMT5 and it demonstrates good brain penetration and significantly prolongs survival in mice with orthotopic glioblastoma models." (PMID 39989968, 2025). "In glioblastoma, PRMT5 inhibition has been suggested to disrupt detained intron (DI) removal, whereas its effects on canonical alternative splicing, such as exon skipping in tumor growth genes, remain relatively minor." (PMID 40846633, 2025). "Overall, this study is the first of its kind that delineates the mechanistic and clinical relevance of PRMT5 in TMZ resistance in glioblastoma." (PMID 39989968, 2025). "Our analysis revealed that PRMT5 expression is positively correlated with DNA damage repair genes across multiple tumor types, including glioblastoma." (PMID 39989968, 2025). "PRT811 is a selective PRMT5 that is used in high-grade gliomas such as glioblastoma or anaplastic astrocytoma." (PMID 40869229, 2025). "Therapies involving the combination of PRMT5 inhibitors and other agents have demonstrated strong cytotoxicity in in vitro models of glioblastoma." (PMID 40450009, 2025). "The functional matrix highlighted multifunctional hubs such as STAT3, TGFB1, and PRMT5, bridging several biological processes central to glioblastoma pathogenesis." (PMID 41179304, 2025). "For instance, MTAP-deficient tumors have shown improved treatment outcomes in various cancers such as pancreatic cancer and glioblastoma by utilizing PRMT5 as a synthetic lethal target." (PMID 38638876, 2024). "In IDH-wildtype glioblastomas, the 2HG-2OG pathway is typically inactive, leading to PRMT5 upregulation." (PMID 38827324, 2024). "Depletion of PRMT5 caused the expression of PTEN transcript and protein expression to significantly increase in the glioblastoma neurospheres." (PMID 38183103, 2024). "In IDH-wildtype glioblastomas, the 2HG-2OG pathway remains inactive, leading to persistent upregulation of PRMT5." (PMID 38827324, 2024). "On the other hand, IDH-wildtype glioblastoma cases that expressed PRMT5 and had unmethylated MGMT-promoter, who received TMZ treatment, have experienced early tumor recurrence." (PMID 38827324, 2024). "Similar predominance of intron retention following pharmaceutical inhibition of PRMT5 has been shown in glioblastoma and haematopoietic cells." (PMID 39313128, 2024). "It was demonstrated that treatment of glioblastoma (GBM) cells with PRMT5 inhibitors compound 5 (CMP5) led to apoptosis of differentiated GBM cells." (PMID 39034387, 2024). "Overall, we confirmed that inhibition of PRMT5 is a promising strategy that should be explored more intensely in the context of treatment of recurrent glioblastoma." (PMID 38383756, 2024). "Both IDH-mutant WHO grade 4 astrocytomas (n = 22, 64.7%) and IDH-wildtype glioblastomas (n = 12, 35.3%) had upregulated PRMT5 gene expression except in one case." (PMID 38827324, 2024). "PRMT5-depletion was shown to sensitize glioblastoma cells to the antitumor effects of the protein phosphatase 2A inhibitor LB100 by facilitating necroptosis." (PMID 36658119, 2023). "By reducing the recruitment of PRMT5 in the glioblastoma cell line, it reduces the methylation of histone." (PMID 38136401, 2023). "For example, recent work by Du and colleagues (2021) highlights the benefit of combining PRMT5 ablation with DNA damage–inducing therapies such as interstrand crosslinks (ICL) agents in glioblastoma." (PMID 37861290, 2023).
glioblastoma (continued). "Recently, the association of PRMT5 with MYC was found in numerous cancers, including brain tumors such as glioblastoma; this association creates abnormalities in MYC function." (PMID 38136401, 2023). "In glioblastoma, PRMT5 inhibition globally increased abnormal splicing events, while mis-spliced transcripts were enriched in cell cycle progression pathways." (PMID 37795443, 2023). "Depletion or inhibition of PRMT5 reduces global H3R2me1 basally enriched at several Fanconi anemia (FA) gene promoters, reducing their expression in glioblastoma." (PMID 37861290, 2023). "Upregulation of PRMT5 is observed in lymphomas, breast cancer, lung cancer, colorectal cancer, and glioblastoma." (PMID 37342192, 2023). "A PRMT5 inhibitor (GSK591 or LLY-283) inhibited the growth of patient-derived glioblastoma stem cells in accordance with splicing alteration levels." (PMID 37342192, 2023). "Recently, protein arginine methyltransferase 5 (PRMT5) overexpression has been shown to be associated with tumorigenic MYC functions in cancers, particularly in brain cancers such as glioblastoma and medulloblastoma." (PMID 38136401, 2023). "For instance, inhibitors of PRMT5, an epigenetic regulator that methylates core proteins of the splicing machinery, were shown to exert strong antitumor effects in glioblastoma through pervasive impairment of intron splicing." (PMID 37599362, 2023). "Several studies reported that PRMT5 and PTEN were linked; PRMT5 reduced PTEN mRNA and protein levels in glioblastoma neurospheres (GBMNS), which significantly increased AKT signaling." (PMID 35493527, 2022). "Interplay between mTOR and PRMT5 has already been identified in different cell types, including T-lymphocytes B-cell lymphoma and glioblastoma." (PMID 35757005, 2022). "Conversely, in glioblastoma, PRMT5 exhibits a tumor suppressive role, while NDRG2 is reported to have oncogenic properties." (PMID 35118387, 2022). "Consistent with the findings, treatment of glioblastoma with PP2A-inhibitor LB100 has an anti-tumor effect in the context of PRMT5 regulation." (PMID 35118387, 2022). "PRMT5 methylates histones and is an epigenetic repressor, and PRMT5 inhibition has antitumor effects in glioblastoma models." (PMID 34948433, 2021). "PRMT5 is overexpressed in multiple cancers, including ovarian, prostate, lung and glioblastoma, where it promotes cancer cell hyperproliferation." (PMID 34168658, 2021). "The metabolic shift in cell energy metabolism is coupled to changes in migration, invasion, and growth, which are mediated by downstream FAK and PRMT5 in glioblastoma cells." (PMID 33807786, 2021). "Taken together, these results indicate an important role for arginine methylation in glioblastoma tumor biology, particularly driven by the overexpression of PRMT5." (PMID 33440687, 2021). "Since the efficacy of EPZ015666 was established, it has been used in multiple experiments to potently inhibit PRMT5 in animal models of glioblastoma and medulloblastoma tumorigenesis." (PMID 33440687, 2021). "Previous studies have shown that PRMT5 levels are elevated in a wide variety of cancer cells including glioblastoma, melanoma, non‐small cell lung carcinoma, lymphoma and leukaemia cells." (PMID 33462997, 2021). "Upregulation of PRMT5 in glioblastoma cells increases their self-renewal capacity and proliferation through the PRMT5–PTEN molecular pathway." (PMID 32392182, 2020). "PRMT5 is also responsible for regulating cellular senescence in glioblastoma neurospheres via Akt and ERK signaling." (PMID 32023548, 2020). "For instance, PRMT5 overexpression or hyperactivation is observed in several tumor types, including acute myeloid leukemia, breast cancer, glioblastoma, lung, and prostate cancer, which facilitates tumor initiation and progression." (PMID 33060569, 2020). "PRMT5 is a promising cancer target in several malignancies including lymphoma and glioblastoma, and PRMT5 inhibitors are in clinical trial against lymphomas and solid tumors." (PMID 31817960, 2019).
glioblastoma (continued). "We have previously shown that Myc induces S-dimethylation of R3 on histone H4 (H4R3me2s, left and ref.33) and associates with PRMT5 in both HEK293T and glioblastoma cells." (PMID 31685892, 2019). "PRMT5 is overexpressed in a number of cancers including melanoma, multiple myeloma, glioblastoma, lung, gastric, prostate, ovarian, and colorectal cancers, and high expression of PRMT5 often correlates with poor patient prognosis." (PMID 30957988, 2019). "Previous studies in neuroblastoma and glioblastoma have demonstrated that PRMT5 can physically interact with MYC and regulate its stability at the post-translational level." (PMID 31694585, 2019). "PRMT5 is found to be overexpressed in many cancer types, including glioblastoma, lung, mantle cell lymphoma, ovarian and prostate cancer." (PMID 29568320, 2018). "High expression of PRMT5 in glioma is associated with high tumour grade and overall poor survival and PRMT5 knockdown provides a survival benefit in an orthotopic glioblastoma model." (PMID 29946150, 2018). "In the present work we show that Myc and Omomyc induce a pronounced, genome-wide, increase in PRMT5-dependent symmetric di-methylation of R3 on histone H4 (H4R3me2s), in 293T and glioblastoma cells." (PMID 26563484, 2015). "Consistently, PRMT5 knock out decreases the proliferation rate of glioblastoma cells as well as their survival and migratory capacity." (PMID 26563484, 2015). "Most recently, expression of the protein arginine methyltransferase PRMT5 was also proposed as an adverse prognostic marker in glioblastoma." (PMID 25602259, 2015). "Indeed, PRMT5 is overexpressed in several cancers including melanoma, multiple myeloma, glioblastoma, lung, bladder urothelial, gastric, ovarian, and colorectal cancers, and PRMT5 expression correlates with poor patient prognosis." (PMID 40864819, 2025). "This mechanistic finding linking PRMT5 to HR and HR to TMZ resistance provides a novel insight and potential solution to overcome TMZ resistance in glioblastoma because, in the combination treatment, as PRMT5 inhibition severely affects the HR repair pathway, it sensitizes GBMNS to TMZ treatment." (PMID 39989968, 2025). "As PRMT5 is a druggable target for glioblastoma, many PRMT5 inhibitors have been developed." (PMID 39989968, 2025). "Taking advantage of a previously published RNA-seq dataset evaluating the splicing outcome of PRMT5 inhibition in a patient-derived glioblastoma cell culture system, we carried out splicing event overlap analyses with our RNA-seq datasets (‘PRMT5 inhibition’ and ‘MDA-MB468-M-H+’ analysis)." (PMID 39862967, 2025). "In glioblastoma, PRMT5 activity conferred therapeutic resistance to mammalian target of rapamycin (mTOR) inhibitors by mediating the methylation of heterogeneous nuclear ribonucleoprotein 1 (hnRNP A1) to promote the translation of cyclin D1 and c-MYC, leading to drug resistance." (PMID 39703687, 2024). "In fact, subsequent inhibition of PRMT5 sensitised the glioblastoma cells to mTOR inhibition." (PMID 39703687, 2024). "Preclinical studies, in vitro and in vivo, revealed that among the PRMT5 inhibitors, treatment of glioblastoma with compound 5 (CMP5) reflects the impact of PRMT5 knockdown, which results in apoptosis of differentiated cells driven into a nonreplicated aging state." (PMID 38827324, 2024). "Recently, PRMT5 has emerged as a promising target for glioblastoma treatment." (PMID 37394580, 2023). "Involvement of PRMT5 in glioblastoma cell growth was identified by shRNA screen." (PMID 37342192, 2023). "depicted the vulnerability of glioblastoma cells to PRMT5 inhibition." (PMID 36959798, 2023). "In addition, PRMT5 silencing or inhibition (EPZ015666) induced antitumor effect in glioblastoma cells in vitro and in an in vivo PDX model by removing detained introns, thereby regulating rapid expression of transcripts associated with proliferation." (PMID 37342192, 2023).